CD47 (CD47 molecule)
Diseases named in the same sentence as CD47 in open-access papers (continued):
Sharing a sentence is not in itself a finding about the gene and the disease.
hepatocellular carcinoma (53 papers, 2014 to 2026). A malignant tumor that arises from hepatocytes. "Furthermore, CD47 is overexpressed on the surface of hepatocellular carcinoma (HCC) cells, and high expression of CD47 is associated with enhanced metastasis of liver cancer cells in transplanted mice." (PMID 32082311, 2020). "Such a construct simultaneously targets glypican-3-positive hepatocellular carcinoma cells and blocks the CD47-SIRP-α axis, thereby promoting macrophage engagement and phagocytosis." (PMID 42318525, 2026). "The precise mechanism via which CD47 modulates cathepsin S secretion in hepatocellular carcinoma and potentially other cell types remains to be elucidated." (PMID 39039207, 2024). "Meanwhile, CD47 regulates tumor initiation and stemness of hepatocellular carcinoma stem cells by triggering the secretion of cathepsin S, which stimulates NF-κB and protease-activated receptor-2 (PAR-2) signaling." (PMID 39039207, 2024). "IL-6 induced CD47 through STAT3 in hepatoma cells, and IL-1β induced CD47 via NF-κB in cervical cancer cells." (PMID 37958404, 2023). "An anti-CD47 antibody in combination with doxorubicin leads to synergistic elimination of hepatocellular carcinoma in mice." (PMID 36860925, 2023). "Although this mechanism seems to be predominantly found in hematologic malignancies, CD47 overexpression was also reported in lung, pancreatic, and hepatocellular carcinoma (HCC)." (PMID 32117287, 2020). "The CD47 mRNA expression was quantified by using real‐time RT‐qPCR for demonstrating CD47 knockdown in Hepa1‐6 hepatoma cells." (PMID 30460349, 2018). "Altered TXNIP mRNA expression was previously reported following CD47 knockdown in hepatocellular carcinoma stem cells." (PMID 26840086, 2016). "While ITGB1 and CD47 are implicated in hepatocellular carcinoma, therapeutic efficacy in HCC models was not evaluated here and will require future validation in hepatocyte-derived and in vivo systems." (PMID 41596257, 2026). "In this study, we suggest an alternative methodological framework for designing potent siRNAs targeting genes implicated in hepatocellular carcinoma, implementing RNA interference mediated by synthetic small interfering RNAs (siRNAs) against mRNAs of ITGB1 and CD47 genes." (PMID 41596257, 2026). "In addition, CDK4 expression correlated with expression of the inhibitory receptor of phagocytosis CD47 in immunohistochemistry sections from hepatocellular carcinomas." (PMID 40699853, 2025). "Importantly, binding of Pal/NRF-1 to the CD47 promoter was also previously reported in human neuroblastoma and hepatoma cell lines, as well as, during arising resistance to the oncogenic B-RAF molecular inhibitors." (PMID 39742254, 2024). "A previous mechanistic study reported that IL-6 derived from TAMs could increase the expression of CD47 in hepatoma cells via activation of the STAT3 pathway." (PMID 34573091, 2021). "In support, NRF-1 regulates CD47 expression in human neuroblastoma and hepatoma cells." (PMID 29050218, 2017). "4-Methylumbelliferone (4Mu) is a hyaluronan synthesis inhibitor that downregulated the expression of CD47 and promoted phagocytosis of intraperitoneal macrophages of hepatocellular carcinoma (HCC) cells." (PMID 39318624, 2024). "For example, the GPC3xCD47 BsAb targets the TAA GPC3, expressed on hepatocellular carcinoma (HCC) cells, and CD47, as well as FcγRs via a functional IgG1 Fc tail." (PMID 35884427, 2022). "Our results also validate recent results observed in a hepatoma cell lines resistant to Sorafenib, where it was proposed that resistance to the drug treatment was associated with high CD47 protein levels achieved by the binding of NFKB2 subunit to the CD47 promoter upon TNF-α stimulation." (PMID 28378740, 2017).
hepatocellular carcinoma (continued). "These patients may benefit from novel MET targeting strategies already available in clinical trials for hepatocellular carcinoma and non-small cell lung carcinoma, as well as from future CD47/SIRPalpha targeting strategies that have proven efficacy in pre-clinical trials." (PMID 25230070, 2014). "Accordingly, the blocking of CD47 was shown to enable macrophage-mediated phagocytosis of CSCs from pancreatic ductal adenocarcinoma (PDAC), AML and hepatocellular carcinoma (HCC), and thus promotes their elimination." (PMID 34572009, 2021). "Further researches on molecular mechanisms showed that activated STAT3 pathway by IL-6 upregulated CD47 expression in hepatocellular carcinoma cell lines, and the IL-6-STAT3 axis blockage reduced cancer cells' antiphagocytic ability via downregulation of CD47 expression." (PMID 35281519, 2022). "For example, in fibrolamellar subtype of hepatocellular carcinoma, CD47 expression did not increase compared to normal hepatic tissue." (PMID 33765961, 2021). "Several studies reported increased expression of THBS1 in hepatic fibrosis and hepatocellular carcinoma, and a recent review summarizes the function of THBS1 and its activity via CD47 in inhibiting NO, cGMP, cAMP and VEGF signalling to promote thrombosis and to decrease tissue survival." (PMID 29296203, 2017). "In hepatocellular carcinoma (HCC), TSP1 can prevent the interaction between CD47 and SIRPα, disrupt the “don’t eat me” signal between hepatoma cells and macrophages, and prevent immune escape." (PMID 37829341, 2023). "Similarly, blockade of CD47 signaling that preserves non-transformed stem cells results in differentiation of breast and hepatocellular carcinoma and stem cells." (PMID 31632920, 2019).
non-Hodgkin lymphoma (53 papers, 2013 to 2025). Distinct from Hodgkin lymphoma both morphologically and biologically, non-Hodgkin lymphoma (NHL) is characterized by the absence of Reed-Sternberg cells, can occur at any age, and usually presents as a localized or generalized lymphadenopathy associated with fever and weight loss. "Magrolimab, the first-in-class anti-CD47 antibody, showed promising results in Phase 1B trials of relapsed and refractory non-Hodgkin’s lymphoma." (PMID 38473748, 2024). "CD47 is expressed ubiquitously on the membrane of various types of cancer, including breast cancer, leiomyosarcoma, myeloma, osteosarcoma, non-Hodgkin’s lymphoma, leukemia, and hepatocellular carcinoma." (PMID 38429732, 2024). "The results showed that the iSNAP-rewired macrophages possessed a strong capability of negating the inhibitory CD47 signaling and eradicating tumors including non-Hodgkin's lymphoma (NHL) and colon cancer." (PMID 35071966, 2022). "According to Advani and others, CD47-blocking antibody Hu5F9-G4 in combination with RTX can benefit patients with non-Hodgkin’s lymphoma." (PMID 34539411, 2021). "Further, in clinical trials, CD47 blockade combing rituximab in non-Hodgkin’s lymphoma showed promising activity." (PMID 34828292, 2021). "As an anticancer treatment, anti-CD47 antibody has shown promising results in non-Hodgkin lymphoma, malignant pediatric brain tumor, lung cancer, and liver cancer." (PMID 33917794, 2021). "Many studies have demonstrated the important role of CD47 in various types of non-Hodgkin lymphomas." (PMID 32677994, 2020). "This is also supported by a recent report of a phase Ib/II study with non-Hodgkin lymphoma patients showing encouraging clinical responses for the combination therapy of anti-CD47 and rituximab." (PMID 30602457, 2019). "Anti-CD47 antibody synergized with rituximab, by promoting phagocytosis, to eliminate lymphoma in both disseminated and localized non-Hodgkin lymphoma (NHL) xenograft models." (PMID 28499452, 2017). "Since then, many different human tumor types such as myeloid leukemia, non-Hodgkin’s lymphoma, bladder cancer and other solid tumors have also been found to express CD47." (PMID 27671753, 2016). "Further, treatment with an anti-CD47 blockingantibody synergized with rituximab treatment to promote phagocytosis in vitro and toeliminate cancer cells in an in vivo xenograft model of non-Hodgkin lymphoma." (PMID 25621565, 2015). "Recently, an anti-CD20 × CD47 bispecific antibody was designed for the treatment of non-Hodgkin lymphoma (NHL), using the dual-variable-domain immunoglobulin (DVD-IgG) format." (PMID 31557983, 2015). "In addition, blockade of CD47 in combination with immunosuppression, including rituximab, is known to be more effective in patients with non-Hodgkin’s lymphoma." (PMID 37368493, 2023). "Notably, CD47 emerges as a potent "Don't eat me" signal, and its excessive presence typifies solid and hematological tumors, encompassing acute leukemia, non-Hodgkin's lymphoma (NHL), colorectal cancers, and ovarian cancers." (PMID 37822610, 2023). "In clinical trials, investigators have started adding anti-CD47 therapy to well-established lines of therapy in different adult cancers, including a successful study in rituximab-resistant non-Hodgkin lymphoma with a humanized anti-CD47 antibody, Hu5F9-G4, and rituximab." (PMID 35582455, 2020). "Anti-CD47 mAb has been shown to synergize with rituximab in the treatment of non-Hodgkin lymphoma." (PMID 25760767, 2015). "In various hematologic malignancies, including AML, acute lymphoblastic leukemia (ALL), and non-Hodgkin lymphoma (NHL), CD47 expression is significantly upregulated." (PMID 40563403, 2025). "CD38 and CD47 are expressed in many hematologic malignancies, including multiple myeloma (MM), B-cell non-Hodgkin lymphoma (NHL), B-cell acute lymphoblastic leukemia (ALL), and B-cell chronic lymphocytic leukemia (CLL)." (PMID 38983860, 2024).
non-Hodgkin lymphoma (continued). "iv) Targeting CD47 with a humanized anti-CD47 monoclonal antibody in combination with rituximab has shown to lead to objective responses in half of the heavily pretreated patients with relapsed or refractory non-Hodgkin's lymphoma, including a complete response in more than one-third of patients." (PMID 38410760, 2024). "In an array of non-Hodgkin lymphoma (NHL) subsets, CD47 was found to be increased on primary NHL cells compared to B cells, which was an independent predictor for worse clinical outcomes." (PMID 34584838, 2021). "In non-Hodgkin’s lymphoma (NHL), CD47 is required for NHL cell extranodal dissemination, which was inhibited by a CD47 blocking antibody." (PMID 36829496, 2023). "As such, diffuse large B-cell lymphoma (DLBCL), the most common subtype of non-Hodgkin’s lymphoma (NHL), was identified as a suitable target for CD47 blocking therapy based on its high SLAMF7 mRNA levels." (PMID 30710089, 2019). "A phase I/II study with the CD47 antibody magrolimab (hu5F9-G4) in combination with the CD20 antibody rituximab revealed mild toxicities and demonstrated encouraging clinical responses in patients with advanced non-Hodgkin’s lymphomas." (PMID 36052078, 2022). "Interestingly, a small retrospective analysis of non-Hodgkin’s lymphoma participants demonstrated a reduction in FDG uptake in the carotid arteries after 9 weeks of Magrolimab treatment, suggesting that CD47 inhibition might reduce vascular inflammation." (PMID 38473748, 2024). "Drugs targeting the CD47 signaling are currently evaluated in clinical studies and are represented by humanized antibodies including Hu5F9-G4 [(in AML, MDS and r/r B-cell Non-Hodgkin Lymphoma (NHL)] and CC-90002 (in AML, MDS and CD20+ NHL patients), respectively." (PMID 32610578, 2020). "For instance, co-treatment of anti-CD20 antibody rituximab with the CD47-blocking murine antibody B6H12 synergized the phagocytic elimination of xenografted human CD20pos non-Hodgkin lymphoma (NHL) cancer cells in murine models in the absence of noticeable toxicity." (PMID 30710089, 2019).
bladder cancer (45 papers, 2015 to 2025). "Fluorescently tagged CD47 antibodies (anti-CD47) enhance bladder cancer cells identification, aiding diagnostic precision and surgical thoroughness." (PMID 39209834, 2024). "Altogether, CD47 was upregulated and associated with poor prognosis in bladder cancer, indicating that it is a potential immunotherapy target for bladder cancer." (PMID 39335665, 2024). "The combination of anti-CD47-QD and blue light cystoscopy showed satisfactory diagnostic accuracy for bladder cancer." (PMID 36290934, 2022). "The combination of anti-CD47-QD and blue light cystoscopy demonstrated promising diagnostic accuracy for bladder cancer in the ex vivo validation study." (PMID 28839158, 2017). "Our results showed that CD47 blockade in bladder cancer caused enhanced angiogenesis in CDX tumor tissues, which might harm anti-tumor efficacy." (PMID 39335665, 2024). "The same group recently reported on the use of CD47 tumor targeting SERS nanoparticles using Raman imaging for the detection of bladder cancer and found similar results supporting the use of CD47 as a diagnostic imaging target to potentially guide transurethral surgery." (PMID 30463284, 2018). "Our previous research has validated the potential of utilizing CD47 as a target for OMI in bladder cancer and upper urinary tract urothelial carcinoma." (PMID 40385528, 2025). "We first analyzed the expression level of CD47 in bladder cancer tissues from 116 patients using IHC staining." (PMID 39335665, 2024). "In summary, dual blocking CD47 and angiogenesis effectively inhibited the growth of bladder cancer and was comparable to combination therapy." (PMID 39335665, 2024). "In this study, we aimed to evaluate the potential of targeting CD47 and angiogenesis in bladder cancer." (PMID 39335665, 2024). "In bladder cancer, there have been attempts at using CD47 antibodies as a targeting domain for molecular imaging and drug delivery." (PMID 39335665, 2024). "Compared with the control antibody treatment, SIRPα-Fc treatment led to significant macrophage phagocytosis of bladder cancer cells expressing CD47 (p < 0.01), confirming the in vitro anti-tumor activity of blocking CD47." (PMID 39335665, 2024). "We then conducted relevant in vitro and in vivo experiments to examine the anti-tumor effect of CD47 blockade in bladder cancer." (PMID 39335665, 2024). "Despite the achievement of anti-CD47 therapy in different cancers, few studies have been conducted to assess the remedial potential of targeting CD47 in bladder cancer." (PMID 39335665, 2024). "After determining that CD47 was a potential target for bladder cancer, we started to investigate the anti-tumor activity of blocking CD47 in bladder cancer." (PMID 39335665, 2024). "To validate the observations from IHC staining, we screened the mRNA expression of CD47 in a bladder cancer cohort, IMvigor210." (PMID 39335665, 2024). "Our study utilized the HSPCs-CDX model to investigate the anti-tumor effects of targeting CD47 and angiogenesis in human bladder cancer." (PMID 39335665, 2024). "Through analyzing 116 bladder cancer tissue samples, we studied CD47 protein expression levels in bladder cancer." (PMID 39335665, 2024). "For example, blocking CD47 with a monoclonal antibody was shown to enable macrophages to phagocytose bladder cancer cells in vivo, inhibit tumor growth, and prevent metastases in xenotransplantation models." (PMID 37373873, 2023). "Unfortunately, studies utilizing human clinical bladder cancer samples to study CD47 expression are limited." (PMID 37373873, 2023). "Due to overexpression of CD47 on the surface of bladder tumor cells, surface of QDs was modified with anti‐CD47 to provide bladder cancer imaging." (PMID 36684065, 2023). "Subsequently, this same group showed that blocking CD47 with a monoclonal antibody enabled macrophages to phagocytose bladder cancer cells in vivo, inhibit tumor growth, and prevent metastases in xenotransplantation models." (PMID 37373873, 2023).
bladder cancer (continued). "CD47-targeted NIR-PIT showed efficacy against human bladder cancer cell lines and patient-derived bladder cancer cells in vitro and in xenograft mouse models." (PMID 35740662, 2022). "CD47 is widely expressed in bladder cancer cells, however, expressed higher in BCSCs than other cancer cells." (PMID 35342431, 2022). "In all paraffin sections investigated, some cells expressed CD276, but only weak signals were observed for CD47 expression in one of three bladder-cancer samples." (PMID 35628262, 2022). "CD47 is expressed on more than 80% of bladder cancer cells but cannot be detected in normal urothelium and the superficial umbrella cell." (PMID 35295998, 2022). "Treatment of mice transplanted with muscle invasive bladder cancer cells using monoclonal anti-CD47 antibodies significantly reduced muscle invasive bladder cancer cells in a dose-dependent manner." (PMID 35903544, 2022). "Blockade of CD47 by targeted monoclonal antibodies enabled macrophage engulfment of bladder cancer cells in vitro and inhibited tumor growth and increased the survival of mouse xenotransplantation models." (PMID 35295998, 2022). "They reported an 82.9% sensitivity and 90.5% specificity for CD47-targeted imaging of bladder cancer with their fluorescent imaging approach, suggesting its potential for improving cancer detection and enabling image-guided surgery." (PMID 30463284, 2018). "Treatment with monoclonal anti-CD47 antibody can induce phagocytosis of macrophages in bladder cancer cells in vitro and significantly reduce tumor growth in bladder cancer xenografts in a dose-dependent manner in the recipient mice." (PMID 29029546, 2017). "We found QD-labeled anti-CD47 specifically localize to the luminal surface of bladder cancer and is a promising imaging agent." (PMID 28839158, 2017). "Previously, we demonstrated successful ex vivo endoscopic imaging of human bladder cancer by topical (i.e. intravesical) administration of QD-conjugated anti-CD47." (PMID 28839158, 2017). "We previously reported targeted molecular imaging of human bladder cancer with QD-conjugated antibody against CD47 (anti-CD47-QD) in fresh intact human bladders from radical cystectomy for invasive bladder cancer." (PMID 28839158, 2017). "However, more evaluations are needed to ensure the safety of combining CD47 blockade and anti-angiogenic drugs in bladder cancer." (PMID 39335665, 2024). "CD47 expression is elevated in several cancers, including bladder cancer." (PMID 39337385, 2024). "Altogether, the results suggest that inhibiting angiogenesis could markedly improve the anti-tumor effect of CD47 blockade in bladder cancer." (PMID 39335665, 2024). "After proving that the combination of CD47 blockade and anti-angiogenic drugs could elicit a potent anti-tumor effect in bladder cancer, we investigated the co-targeting effect of simultaneously blocking CD47 and angiogenesis." (PMID 39335665, 2024). "In bladder cancer, CD47 expression has been reported to be higher in T1 tumors." (PMID 39337385, 2024). "The results showed that targeting CD47 and angiogenesis could be a potential strategy for treating bladder cancer, and anti-angiogenic drugs could improve the efficacy of anti-CD47 immunotherapy." (PMID 39335665, 2024). "We also investigated the role of angiogenesis in CD47 blockade therapy, and we further explored whether combining CD47 blockade with anti-angiogenic drugs could deliver a stronger anti-tumor effect in bladder cancer." (PMID 39335665, 2024). "We then combined CD47 blockade with anti-angiogenic drugs to treat bladder cancer and discovered that inhibiting angiogenesis could further improve the anti-tumor effect of CD47 blockade (TGI: 76.39%)." (PMID 39335665, 2024). "In conclusion, our works demonstrated that CD47 is a suitable target in bladder cancer, and targeting CD47 in bladder cancer could exert a decent in vitro and in vivo anti-tumor effect." (PMID 39335665, 2024).